FAM81B (family with sequence similarity 81 member B)
Synonyms: FLJ25333
Tractability: PROTAC: ubiquitination databases record sites on it.
Gene: Protein-coding gene on chromosome 5 (95,391,366 to 95,450,454, forward strand). Ensembl gene ENSG00000153347.
Gene Ontology:
Molecular function: protein binding
Cellular component: nucleus
Genetic constraint (gnomAD): Loss-of-function variants: 54 observed, 54.48 expected, observed/expected ratio (o/e) 0.99, 90% interval 0.8 to 1.24. The upper end of that interval is the gene's LOEUF score, 1.24, which puts it in group 5 of 6, group 1 being the genes least tolerant of losing a copy. Missense variants: 468 observed, 512.75 expected, observed/expected ratio (o/e) 0.91, 90% interval 0.85 to 0.99. Synonymous variants: 182 observed, 179.64 expected, observed/expected ratio (o/e) 1.01, 90% interval 0.9 to 1.15.
Homologues: Orthologues: chimpanzee FAM81B (98% identical), pig FAM81B (80% identical), dog FAM81B (77% identical), rabbit FAM81B (75% identical), rat Fam81b (74% identical), mouse Fam81b (73% identical), guinea pig FAM81B (72% identical), tropical clawed frog fam81b (38% identical), zebrafish fam81b (15% identical). Paralogues in human: FAM81A (27% identical).
Diseases named in the same sentence as FAM81B in open-access papers:
FAM81B is named in the same sentence as 2 diseases in open-access papers, as found by Europe PMC text mining. Sharing a sentence is not in itself a finding about the gene and the disease. The quoted sentences say what the papers report.
breast carcinoma (1 paper, 2018). "Expression of FAM81B is related to progression free survival of estrogen positive breast cancer when treated with aromatase inhibitors." (PMID 30237808, 2018).
FAM81B also shares sentences with these, for which no sentence is quoted: Obesity (1 paper).